CD34 (CD34 molecule)
Description:
Possible adhesion molecule with a role in early hematopoiesis by mediating the attachment of stem cells to the bone marrow extracellular matrix or directly to stromal cells. Could act as a scaffold for the attachment of lineage specific glycans, allowing stem cells to bind to lectins expressed by stromal cells or other marrow components. Presents carbohydrate ligands to selectins.
Tractability: Antibody: its Gene Ontology location is reachable by antibodies, with high confidence; UniProt predicts a signal peptide or a membrane-spanning region; the Human Protein Atlas places it where antibodies can reach.
Gene: Protein-coding gene on chromosome 1 (207,880,972 to 207,911,402, reverse strand). Ensembl gene ENSG00000174059.
Subcellular location: Membrane
Subcellular location (Human Protein Atlas): Cell Junctions; Plasma membrane; Nucleoplasm
Pathways (Reactome):
Immune System: Immunoregulatory interactions between a Lymphoid and a non-Lymphoid cell
Gene Ontology:
Molecular function: carbohydrate binding; protein binding; RNA polymerase II-specific DNA-binding transcription factor binding; sulfate binding
Biological process: cell motility; cell-cell adhesion; endothelial cell proliferation; endothelium development; extracellular exosome assembly; glomerular endothelium development; glomerular filtration; hematopoietic stem cell proliferation; hemopoiesis; metanephric glomerular mesangial cell differentiation; negative regulation of gene expression; negative regulation of interleukin-2 production; paracrine signaling; positive regulation of angiogenesis; positive regulation of gene expression; positive regulation of granulocyte colony-stimulating factor production; positive regulation of odontogenesis; positive regulation of vasculogenesis; signal transduction; stem cell proliferation; tissue homeostasis; transdifferentiation; vascular wound healing; cell-matrix adhesion; leukocyte migration; and 2 more
Cellular component: cytoplasm; external side of plasma membrane; intercellular bridge; perinuclear region of cytoplasm; plasma membrane; apical plasma membrane; basal plasma membrane; glomerular endothelium fenestra; lysosome; cell periphery; cell surface; extracellular region; membrane
Genetic constraint (gnomAD): Loss-of-function variants: 33 observed, 37.28 expected, observed/expected ratio (o/e) 0.89, 90% interval 0.67 to 1.18. The upper end of that interval is the gene's LOEUF score, 1.18, which puts it in group 5 of 6, group 1 being the genes least tolerant of losing a copy. Missense variants: 423 observed, 461.43 expected, observed/expected ratio (o/e) 0.92, 90% interval 0.85 to 0.99. Synonymous variants: 207 observed, 187.57 expected, observed/expected ratio (o/e) 1.1, 90% interval 0.99 to 1.24.
Homologues: Orthologues: macaque CD34 (91% identical), chimpanzee CD34 (82% identical), rabbit CD34 (71% identical), dog CD34 (67% identical), mouse Cd34 (65% identical), pig CD34 (65% identical), guinea pig CD34 (62% identical), rat Cd34 (50% identical), zebrafish cd34 (15% identical), zebrafish si:ch211-286o17.1 (15% identical).
Diseases named in the same sentence as CD34 in open-access papers:
CD34 is named in the same sentence as 839 diseases in open-access papers, as found by Europe PMC text mining. Sharing a sentence is not in itself a finding about the gene and the disease. The quoted sentences say what the papers report.
leukemia (617 papers, 2005 to 2026). A malignant (clonal) hematologic disorder, involving hematopoietic stem cells and characterized by the presence of primitive or atypical myeloid or lymphoid cells in the bone marrow and the blood. "CD34+ leukemias exhibited overexpression of genes associated with stemness, migration, adhesion, and survival." (PMID 40792274, 2025). "We took advantage of the MYC-GFP reporter to enumerate the specific impact of CHMP5 deficiency on leukemia-initiating cells (LIC) wherein LICs in ICN1-driven T-ALL express CD34 and MYC13,66." (PMID 40319015, 2025). "In their study, which capped the maximum CD34+ cell dose at 8 × 106/kg, higher doses were associated with improved outcomes, likely due to more rapid engraftment and enhanced graft-versus-leukemia (GVL) effects." (PMID 40773143, 2025). "In the field of oncology, CD34 serves as a classical CSC marker in leukaemia and is closely associated with disease onset, progression and drug resistance." (PMID 40665579, 2025). "Patients with short EFS and long EFS expressed comparable amounts of leukemia-associated antigens CD34, CD123, and CD117." (PMID 38253683, 2024). "Another study identified a leukemia-associated immunophenotype (LAIP) of CD25+/CD34+/CD99+/CD123+ that is strictly associated with FLT3 ITD in AML with NPM1 mutation and a normal karyotype." (PMID 39594810, 2024). "Here, we demonstrated, in a fourth PDX model followed for 7 months after AML injection, that TCRFLT3D/Y cells in vitro can specifically and efficiently target and kill leukemia-propagating CD34+ FLT3D835Y-mutated AML cells." (PMID 37783807, 2023). "For example, upregulation of FOXO1 in AML with a RUNX1 mutation has been reported to help the growth of leukemia cells and inhibit the differentiation of CD34 + hematopoietic stem and progenitor cells." (PMID 38007419, 2023). "Even at remission, residual CD34+ progenitors as well as mature cells isolated from AML samples have been shown to harbor some of the mutations from the original leukemia." (PMID 37345204, 2023). "Since conventional flow cytometry evaluation showed significant differences between leukemia cells derived from High and Standard-risk patients when two surface markers were analyzed (sGRP78 in combination with CD34, CD38, CD10 or CXCR4)." (PMID 35149705, 2022). "The protein profile of these sEV is enriched in leukemia-associated antigens (LAAs), such as CD34, CD123, CD96, CLL-1, suggesting these are leukemia blast-derived sEVs." (PMID 34296216, 2021). "CXCR4 expression levels in CD34+ leukemia cells are associated with poor survival and higher probability of relapse in AML patients." (PMID 32754595, 2020). "Healthy HSPCs were obtained by magnetic association cell sorting (MACS) and CD-34 micro-beads from umbilical cord blood samples and then, were treated with 20 and 40 μg/ml leukemia microvesicles for 10 days, respectively." (PMID 31548916, 2019). "We have also tested possible association between PD-L1 and CD34 positivity, the latter being one of the stemness markers of leukemia cells." (PMID 31185600, 2019). "CpG islands were reported as the sites most strongly overlapping with H3K9me2 peaks in CD34+ hematopoietic progenitors while many leukemia-deregulated genes are associated with the areas of normally low DNA methylation (“canyons”)." (PMID 28301528, 2017). "Podocalyxin (PCLP1) is a CD34-related sialomucin expressed by some normal cells and a variety of malignant tumors, including leukemia, and associated with the most aggressive cancers and poor clinical outcome." (PMID 29245936, 2017). "This phenomenon (missing self-theory) was described by the Perugia group as the key event responsible for the cure of high risk leukemia following CD34 selected haploidentical graft." (PMID 27110243, 2016). "At last we substituted the combination for analysis of dendritic cells and basophils for a combination (CD7/CD56/CD45/CD34) to assess the most frequent leukemia-associated phenotypes." (PMID 25924846, 2015).
leukemia (continued). "The incidences of LTLS in the traditional high risk groups were as follows: age >60 years 28.8%, primary AML 26.8%, secondary AML 25%; WBC >100x109/L 50%, LDH >2xULN 21.6%, CD34+ leukemias 16.3%, NPMI 27.2% and FLT3 gene mutation 33.3%." (PMID 25775138, 2015). "In CD34-positive AML cases, CD34+CD38– cells that express aberrant leukemia-associated immunophenotypic markers are neoplastic." (PMID 24244383, 2013). "The availability of “healthy” human hematopoietic CD34+ progenitor cells and retroviral vector technology facilitates the establishment of models used to analyze human leukemic CD34+ progenitor cell expansion driven by leukemia-associated gene products." (PMID 24348510, 2013). "Additionally, the immunophenotypic strategy employed showed a high specificity, with lymphoblastic cells consistently expressing established leukemia-associated markers and a distinctive CD34++CD38−/dim expression profile." (PMID 40076750, 2025). "In these NPM1-mutated leukemias, the LSCs can also be found in the CD34– population." (PMID 41424935, 2025). "Interestingly, this study showed a significant association between CD123 and CD25 expression in leukemia CD34+ cells." (PMID 36769040, 2023). "Furthermore, targeted protein profiling of leukemia-associated antigens CD34 and CD117 in AML EVs versus control EVs showed differential representation of these markers, which were higher in AML than controls." (PMID 38023151, 2023). "As expected, genes associated with AML proliferation (FLT3, KIT), leukemia stem cells (CD34, CD38, and IL1RAP), and candidate genes overexpressed in AML (CD99, CD200, and LAMP2) were downregulated after chemotherapy, consistent with recent scRNA-Seq and immunohistochemistry data." (PMID 36099049, 2022). "The transmembrane protein smoothened (SMO), an essential regulator of Hh signal transduction, is highly expressed in CD34+ leukemia cells and can activate downstream glioma-associated oncoprotein (GLI) transcription factors to maintain the dormancy and chemoresistance of LSCs." (PMID 35865470, 2022). "Thus, both the number of CD34‐positive cells within the leukemia and the overall CD34 MFI level seemed to be associated with the induction therapy response." (PMID 35271751, 2022). "Consequently, leukemia engraftment in patient-derived xenograft mice bearing CD34+ TKI-resistant CML blasts carrying PTPN11 mutation responsible for hyperactivation of the RAS/RAF/MAPK and JAK/STAT5 pathways was decreased upon double treatment." (PMID 36460969, 2022). "A retrospective analysis of more than 100 patients under 65 years of age with de novo AML indicated that higher percentages of CD34+/CD38−/CD123+ leukemia cells at diagnosis associate with enhanced probability of resistance to intensive chemotherapy and shorter disease-free survival." (PMID 33322769, 2020). "While the relative susceptibility of leukemia cell lines may be due to loss of function, the similar phenotype observed in primary CD34+ cells suggests that this may instead reflect an immature progenitor phenotype." (PMID 28031367, 2017). "Because of the genetic similarities found in the fast engrafting T-ALL, we investigated whether CD34 expression is associated with enhanced leukemia development because of its implication in migration/adhesion." (PMID 27191650, 2016). "The negative impact of CD200 on remission probability was maintained in multivariate analysis (p = 0.04), along with more conventional factors such as age (p = 0.002), type of leukemia (p = 0.002), CD34 positivity (p = 0.008) and unfavorable cytogenetic risk (p = 0.0025)." (PMID 26338961, 2015). "Moreover, increase in number of CD34+ progenitors, as well as their phenotypic abnormalities corresponding to leukemia-associated phenotypes (LAIPs), are also frequently found." (PMID 24324660, 2013).
leukemia (continued). "CD34+ cell lines display natural resistance to mitoxantrone associated with an absence of apoptosis, giving these immature myeloid leukemia cells a survival advantage over the more mature leukemia hematopoietic compartment." (PMID 21595920, 2011). "This plasticity of tumor stem cells may also apply to liquid tumors, as it was recently shown that leukemia-initiating cells in AML patients harboring mutations in nucleophosmin (NPM) can reside in the CD34+ as well as CD34- fraction." (PMID 21179426, 2010). "CCL21 has also been implicated in the abnormal adhesion and migration of CD34+ cells in leukemia." (PMID 17506907, 2007). "However, FC already is a routine diagnostic tool employed to enumerate CD4+ T cells and CD34+ progenitor cells and to screen for HLA-B27 antigen and leukemia/lymphoma immuno-phenotyping." (PMID 16472397, 2006). "This hypothesis is further supported by a recent leukemia model-based study that AML cells with low ROS were enriched within the leukemia-initiating cells that had higher percentages of CD34+CD38- cells, reflecting the reverse association between ROS level and differentiation." (PMID 38434766, 2024). "However, since initial analysis of leukemia cells by ImageStream showed coexpression of CD34 and sGRP78 in single cells derived from High and Standard-risk patients, we decided to analyze a set of classical surface antigens on leukemia cells." (PMID 35149705, 2022). "Our analysis suggests the existence of dedifferentiating transitions to a CD34+/CD38− stem cell–like immunophenotype in leukemia samples collected from patients with B-ALL, and the tendency for these transitions is especially strong in B-ALL with BCR::ABL1." (PMID 41295979, 2026). "The progeny of transplanted CD34+/CD38− leukemia cells acquired lineage-specific markers and reproduced the French–American–British classification of the original human AML specimen, consistent with in vivo differentiation." (PMID 41295979, 2026). "Here, we investigated the role of CTCF during erythroid differentiation using two complementary models: pluripotent K562 leukemia cells and primary human CD34+ hematopoietic stem/progenitor cells, each induced toward the erythroid lineage by distinct stimuli." (PMID 42072669, 2026). "Because all selected patients had clinically confirmed CD34-positive leukemia cells via flow cytometry and pathology at the time of biopsy collection, we used the CD34 protein channel to identify leukemia cells." (PMID 40632867, 2025). "RNA-seq analysis of A485-treated K/C-III leukemia cells further revealed significant downregulation of key hematopoietic factors, including Hoxa9, Hoxa10, Meis1, Cd34, c-Kit, and Csf1r." (PMID 40830799, 2025). "The CD117×CD3 BTCE was not toxic and facilitates highly efficient engraftment of human allogenic donor CD34+cells in humanized mice, thereby restoring hematopoiesis in vivo in both normal and leukemia-bearing humanized mice." (PMID 40579234, 2025). "The criteria that patients needed to have CD34+ leukemia for inclusion in the spatial transcriptomic analysis limited the cohort size to six patients." (PMID 40632867, 2025). "Consistently, the mRNA expression of PRMT1 was higher in leukemia stem/progenitor cells (LSPCs) sorted from individuals with CML (CML CD34+) than in hematopoietic stem/progenitor cells (HSPCs) sorted from healthy donors (normal CD34+)." (PMID 39668478, 2025). "High MYC and CD34 expression define T-ALL cells with leukemia-initiating cell (LIC) properties in activated NOTCH1-driven T-ALL13,66." (PMID 40319015, 2025). "CSCs were primarily discovered in leukemia as characterized by the CD34+/CD38− phenotype by John and Bonnet in 1997 and were subsequently identified in solid tumors such as colon, breast, ovarian, pancreatic, hepatocellular carcinoma and thyroid cancer." (PMID 41233805, 2025).
leukemia (continued). "We analyzed RNA-seq data from CD34 + normal hematopoietic stem/progenitor cells (HSPCs) or AML leukemia stem cells (LSCs) derived through in vitro differentiation from these lines (GSE92494)." (PMID 39863913, 2025). "Nevertheless, other studies showed that B7-H4 is expressed only in a subset of CD34+ leukemia stem cells and CD133+ brain CSCs/CICs, specifically the non-dividing (quiescent) fraction." (PMID 41233805, 2025). "Since all selected patients had CD34-positive leukemia cells, we used the CD34 protein channel information to identify leukemia cells." (PMID 39975227, 2025). "Consistent with our pooled screening results, KRAB-mediated repression of the CEBPA +42 kb cisRE resulted in decreased CEBPA expression and maintained leukemia cells in a CD34+ stem cell–like state following MECOM degradation." (PMID 40991835, 2025). "The criteria that patients needed to have CD34+ leukemia for inclusion in the spatial transcriptomics analysis limited the cohort size to 6 patients." (PMID 39975227, 2025). "In sharp contrast, stem cell gene, Cd34; lineage gene, Gata2; and leukemia stem cell regulator, Ikzf2; as well as Tnfaip3, Pvr (Cd155), and Nectin2 (Cd112), were upregulated in Vav-cre Tet2fl/flTp53fl/fl GMPs." (PMID 40111422, 2025). "Yet leukemia-initiating capacity is detected also in CD34+CD38+ and in CD34- cell clones; which, however, in general, have a decreased capacity for leukemia initiation." (PMID 40643557, 2025). "In the context of leukemia, MZF1 was found to inhibit the differentiation of hematopoietic stem cells by suppressing the activity of the CD34 or c-myb promoters, thereby impeding differentiation and facilitating the emergence of a leukemia-like phenotype." (PMID 40655141, 2025). "Leukemia cells were thereby identified based on cell morphology and the CD34 protein expression pattern, which enabled us to exclude CD34-expressing endothelial cells." (PMID 39975227, 2025). "K562 CML leukemia cells and primary CD34 + CML blasts were cultured alone or co-cultured with HS-5 stromal cells to mimic the bone marrow microenvironment conditions." (PMID 41331927, 2025). "We demonstrated that patients with lower-risk MDS and low CD34 + CD38+HSPCs entropy had an adverse outcome and that this parameter is as an independent predictive biomarker for progression free survival, leukemia free survival and overall survival." (PMID 38575672, 2024). "Our findings that CD116 is upregulated in the CD34+ progenitors is interesting as it raises the question of the effect of GM-CSF on the leukemia-initiating cell population." (PMID 39298477, 2024). "Using previously established MLL-AF9 leukemia model that inducing umbilical cord blood CD34+ cells develop into AML cells by MLL-AF9 fusion gene." (PMID 38693103, 2024). "Given our results on the metabolic profiling of AML cells and the distinct phenotype and cargo of EVAML, we then investigated the functional influences of EVAML on the redox metabolism of various human leukemia cell lines and primary CD34+ AML cells." (PMID 39738118, 2024). "Unsupervised hierarchical clustering indicated that CIMP leukemia constitutes a separate subgroup with strong hypermethylation, particularly at regions hypomethylated in CD34+ cells." (PMID 38972954, 2024). "In leukaemia stem cells, it inhibited proliferation and activated the intrinsic apoptotic pathway, with apparently low effects on normal CD34+ haematopoietic cells." (PMID 38612718, 2024). "Two of these clusters were “leukemia-related” containing a great proportion of CD34+/CD38− hematopoietic stem cells (HSCs) or CD34+ cells with a strong co-expression of CD45RA/CD123, respectively." (PMID 38610998, 2024). "The potential involvement of HOX genes in both cytopenias and leukemias require the need to regulate HOX expression of the CD34+ HSPCs so that the balance is maintained between these two pathogenic conditions and either disease extremities are not exacerbated." (PMID 38721526, 2024).